ACE (angiotensin I converting enzyme)
Diseases named in the same sentence as ACE in open-access papers (continued):
Sharing a sentence is not in itself a finding about the gene and the disease.
Hypertension (continued). "Ang-I is transformed by the angiotensin-converting enzyme (ACE) into the octapeptide Ang-II that regulates blood pressure and is a key player in hypertension." (PMID 33401711, 2021). "Modulation of the RAS has been suggested to participate in the development of hypertension in L-NAME-treated rats, as increased angiotensin-converting enzyme (ACE) activity has been observed in serum and tissue in this animal model." (PMID 33801631, 2021). "Angiotensin-converting enzyme inhibitors (ACE-i) and angiotensin II receptor blockers (ARB) for hypertension were prescribed to 75.4% of the patients, while hyperlipidemia was treated mainly with statins (90.4%)." (PMID 34646868, 2021). "Our previous study showed that trichostatin A, a HDAC inhibitor, prevented neonatal DEX-induced programmed hypertension accompanied with decreases of AGT, ACE, and ACE2." (PMID 33669059, 2021). "Ang II type 1 receptor antagonists, as well as angiotensin-converting enzyme (ACE) and renin inhibitors, are widely used for treatment of hypertension." (PMID 33688433, 2021). "We recommend that patients with cardiac diseases, hypertension, or diabetes that are treated with ACE2-increasing drugs may be at higher risk for severe COVID-19 infection and that, therefore, ACE2-modulating therapies like ACE inhibitors or ARBs should be supervised attentively." (PMID 34828513, 2021). "The antagonistic roles that ACE and ACE2 play in inflammation and anti-inflammation are crucial to physiological homeostasis and pathophysiology in the development of hypertension, renal diseases, and ARDS." (PMID 33390179, 2021). "In this case series, enalapril, an angiotensin-converting enzyme (ACE) inhibitor, was started in neonates with systemic hypertension and echocardiography signs of LV diastolic dysfunction." (PMID 34640535, 2021). "For this model, selected variables were hypertension, antihypertensive medicine, triglycerides, duration of IDDM, drinker, daily insulin dose, age, ACE inhibitors, BMI, HbA1c, and LDL." (PMID 34943504, 2021). "In hypertension, the function of ACE2 is to vasodilate and reduces blood pressure primarily by antagonizing the ACE/Ang II/AT1R axis, which can also affect the NO signal pathway in the CNS." (PMID 33443816, 2021). "Moreover, hypertension is a frequent AE of antiangiogenic therapy, and antihypertensive drugs such as angiotensin II type 1 receptor blockers ARBs) or angiotensin-converting enzyme (ACE) inhibitors may affect expression of the ACE2, the receptor of SARS-Cov-2." (PMID 33085057, 2021). "According to the BIOPEP-UWM database, the potential ACE and DPP-IV inhibitory capacity, which are related to hypertension and type 2 diabetes was outstanding." (PMID 34681387, 2021). "ACE inhibitors and AT1-blockers are widely prescribed for the treatment of hypertension and congestive heart failure in humans." (PMID 35366262, 2021). "In another renal programming model induced by placental insufficiency in the Sprague Dawley rat, adult offspring developed hypertension in conjunction with increased renin and AGT mRNA, as well as increased ACE activity at 16 weeks of age." (PMID 33669059, 2021). "Under pathological conditions, the ACE-Ang II-AT1 axis becomes over-activated, and RAS activity increases, leading to hypertension, atherosclerosis, hypertrophy, type 2 diabetes, and kidney fibrosis." (PMID 33841179, 2021). "In conclusion, ACE-inhibitory peptides produced from salmon bone hydrolysates have shown the potential to efficiently block ACE activity in vitro and may thus play a role in the development of future medications that may be used to address the problem of hypertension." (PMID 34473745, 2021). "Indeed, hypertension, one of the major risk factors for strokes, induces a structural narrowing of the cerebral arterial lumen (thus reducing blood perfusion in case of a stroke) that only antihypertensive treatments targeting RAS and AT1 stimulation (ACE inhibitors and/or ARBs) are able to prevent." (PMID 34201646, 2021).
Hypertension (continued). "Combining the outcomes from both target lists, we selected ACE, AGT, AGTR1, and REN as important targets in COVID-19 for hypertension patients." (PMID 34067609, 2021). "Lisinopril, an ACE inhibitor, was used as a positive control substance to prevent L-NAME-induced hypertension and cardiac abnormalities in rats here." (PMID 33557258, 2021). "Ang II, as a key mediator in hypertension, is mainly produced from angiotensinogen (ATG) via angiotensin-converting enzyme (ACE)." (PMID 34413926, 2021). "The Angiotensin-converting enzyme (ACE) inhibitors and Angiotensin Receptor Blockers (ARBs) are the drugs of choice for the control of high blood pressure and are indicated starting from grade 1 AH." (PMID 33809389, 2021). "This study found that high blood pressure and male sex shift the RAS balance in the lungs towards the vasoconstrictive, profibrotic, and proinflammatory ACE/Ang II axis." (PMID 34751382, 2021). "Pathophysiology of hypertension in SHR is due to overall changes in RAS components, such as renin activity, ACE activity, angiotensin II content, AT1 receptor expression, and NADPH oxidase activity." (PMID 32325920, 2020). "Because of its central role in hypertension, various anti-hypertensives drugs were developed that target the A-II/AT1 receptor axis; ACE inhibitors (ACE-Is) and Angiotensin Receptor Blockers (ARBs)." (PMID 32793221, 2020). "ACE inhibitors (ACEi) and ARBs that affect the renin–angiotensin–aldosterone system (RAAS) are commonly recommended for patients with hypertension." (PMID 32585855, 2020). "As a key regulator of blood pressure, angiotensin-converting enzyme (ACE) was also the binding site of SARS-CoV, making hypertension the most focused comorbidity." (PMID 32658868, 2020). "For instance, ACE inhibitors (ACEI) and angiotensin-receptor blockers (ARB) are common drugs for cardiovascular disorders, such as hypertension." (PMID 32765943, 2020). "Enalapril, an orally active inhibitor of the angiotensin converting enzyme (ACE), is widely used for the treatment of hypertension and heart failure." (PMID 32547398, 2020). "A zinc metalloenzyme, angiotensin-converting enzyme (ACE) was discovered 64 years ago and first named as a hypertension-converting enzyme." (PMID 33112891, 2020). "Our previous work demonstrates the beneficial role of ACE, AT1R, and AT2R against hypertension-induced cardiac hypertrophy by EA applied at the bilateral PC6 acupoints." (PMID 32982761, 2020). "Angiotensin-converting enzyme inhibitors (ACE) and angiotensin II receptor blockers (ARB) are commonly used for the treatment of patients with heart disease, hypertension (HTN), and diabetes mellitus (DM)." (PMID 32905551, 2020). "Through the reduction of multifactorial dimensionality, it can be verified that there is a close and strong genotype interaction between ACE and NOS3 that in turn relates to hypertension as well as to hypercholesterolemia, smoking, and red meat intake." (PMID 32714484, 2020). "Hypertension, heart failure (HF) and ischemic heart disease are often treated with renin-angiotensin-aldosterone system (RAAS) blockers such as angiotensin-converting enzyme (ACE) inhibitors or angiotensin receptor blockers (ARBs)." (PMID 33195473, 2020). "In this study we have shown that unfiltered VOO contains small peptides with specific ACE inhibitory activity and antihypertensive effects on the SHR animal model of hypertension." (PMID 31968696, 2020). "Angiotensin Converting Enzyme (ACE) is a central component of RAS (given its role in the generation of Ang II), and is a principal target in the management of cardiovascular (hypertension, heart failure, post myocardial infarction) and renal diseases." (PMID 32217149, 2020). "Angiotensin-converting enzyme inhibitors (ACE) and angiotensin II receptor blockers (ARB) have been among the first-line medications in the treatment of patients with hypertension (HTN), diabetes mellitus (DM), and heart disease." (PMID 32905551, 2020).
Hypertension (continued). "Age, gender, hypertension, CCI, ACE inhibitor, ARB, anticoagulant agents, gemfibrozil, statins, and hypoglycemic agents were adjusted in this study." (PMID 32751875, 2020). "The PVN is a vital cardiovascular center which expresses major RAS components, such as AGT, ACE-1, AT1, and contributes to hypertension in CKD." (PMID 31392659, 2020). "Activation of RAS, such as high levels of serum Ang II, renin, ACE activity, and AT1R expression in LHR has been observed, and has contributed to hypertension and vascular remodeling in this animal model." (PMID 33007813, 2020). "Existing treatment options for hypertension include pharmaceutical drugs that target the RAS pathway such as angiotensin receptor antagonists, ACE inhibitors and ACE2 activators." (PMID 32366012, 2020). "Clinical data suggested that application of ACE inhibitors and ARB contribute to the clinical outcomes of COVID-19 patients with hypertension." (PMID 32490731, 2020). "Hypertension is regulated by the renin-angiotensin system (RAS), through modulating the angiotensin-converting enzyme ACE, bradykinin and other factors." (PMID 32013233, 2020). "SARS-CoV-2 inhibition of ACE2 promotes ACE/Ang II/AT1R activity, leading to hypertension-induced SP production." (PMID 32922297, 2020). "In clinical practice, angiotensin-converting enzyme inhibitors (ACE-Is) and angiotensin II receptor blockers (ARBs) are extensively used for the treatment of hypertension and other cardiovascular diseases." (PMID 32430651, 2020). "In univariate analysis the risk factors for developing AF in the acute phase of infarction were: female sex, age, hypertension, smoking HR on Holter, CRP > 3 mg/L, eGFR, log-NTproBNP, chronic use of ARB/ACE inhibitors and chronic use of beta-blockers." (PMID 32423138, 2020). "It is known that ACE converts Ang I into Ang II, which is critical in promoting VSMC migration via AT1 receptors, and is involved in vascular remodeling in hypertension." (PMID 32121598, 2020). "Remarkably, our previous work has endeavored the influential role of Angiotensin-converting enzyme (ACE), AT1R, and AngII type 2 receptor (AT2R) on the pathological progression from hypertension to cardiovascular remodeling in SHR by EA treatment." (PMID 32982761, 2020). "Using 4,150 Thais recorded in the Electricity Generating Authority of Thailand (EGAT) study, we examined the association of rs1799752, rs699, rs5186, and rs1799998 located in or near ACE, AGT, AGTR1, and CYP11B2 genes in hypertension." (PMID 31511791, 2019). "In this study, VDD+AmB/LE rats developed hypertension, accompanied by a notable increase in renal protein expression of AGT and ACE, and higher levels of plasma aldosterone." (PMID 31295336, 2019). "In addition, it has been observed that probiotic supplementation caused a decrease in ACE activity measured in the serum of SHR treated with the soluble nonbacterial fraction of kefir, supporting ACE inhibition as a likely mechanism for kefir's beneficial cardiovascular effects during hypertension." (PMID 31205584, 2019). "On the other hand, RAS-blocking agents, such as angiotensin converting enzyme (ACE) inhibitors and AT1 receptor blockers (ARBs), have been shown to be effective in the management of hypertension-related cardiovascular diseases and end-organ damage." (PMID 30934934, 2019). "The 2K1C model was chosen because hypertension is due mainly to upregulation of the RAAS system, so model rats respond well to ACE inhibitors such as captopril." (PMID 31379972, 2019). "Angiotensin-converting enzyme (ACE) is considered crucial in this pathway and has received considerable attention as a therapeutic target for controlling hypertension." (PMID 30875817, 2019). "Angiotensin-converting enzyme (ACE) inhibitors are among the most common medications used to treat patients with concomitant diabetes and hypertension." (PMID 31489273, 2019).
Hypertension (continued). "In this study, we produced miso that has high ACE inhibitory activity (shinki miso) and investigated its hypotensive properties in SHRSP/Izm, a genetic model of spontaneous hypertension." (PMID 30631160, 2019). "Asparaptine has been proposed to have inhibitory activity against the angiotensin-converting enzyme (ACE), which plays a role in hypertension regulation in humans." (PMID 31881716, 2019). "Regarded as an efficient strategy of anti-hypertension (AHT), ACE inhibitors have been studied for years." (PMID 31758024, 2019). "Two health organization, namely the international society of hypertension-world health organization (ISHWHO) and the Canadian society of hypertension recommend ACE inhibitors as the first line of treatment for hypertension." (PMID 31336853, 2019). "A combination of an angiotensin-converting enzyme (ACE) inhibitor and an angiotensin II receptor antagonist is recommended in treating patients with essential hypertension and left ventricular hypertrophy." (PMID 31277258, 2019). "The classical RAS, defined as the ACE-angiotensin (Ang) II-AT1R axis, promotes vasoconstriction and sodium retention, leading to hypertension." (PMID 30127255, 2018). "The three main types of hypertension drugs, i.e. beta blocking agents (ATC:C07AB), ACE-inhibitors (ATC:C09AA) and dihydropyridine derivatives (ATC:CO8CA), thus result in very different systemic effects on the plasma proteome." (PMID 29615742, 2018). "ACE plays a critical role in RAS signaling: It produces angiotensin II (the main vasoconstrictor peptide), which activates pathways leading to hypertension and fibrosis, while also degrading bradykinin." (PMID 30618804, 2018). "Antihypertensive drugs such as ACE inhibitors and ARB are widely used for the management of hypertension and the prevention of cardiovascular disease events in high-risk persons." (PMID 29514670, 2018). "RAS inhibitors, including ACE inhibitors, ANG II receptor blockers, and renin inhibitors are commonly used in the treatment of hypertension." (PMID 29540174, 2018). "The ACE inhibitors and the AT1 receptor blockers reduce mitochondrial dysfunction related to age, attenuate the renal mitochondrial dysfunction induced by hypertension, and protect against cardiac mitochondrial dysfunction from acute ischemia." (PMID 29849615, 2018). "ACE was the target of inhibitor drugs, such as ramipril, trandolapril, and benazepril, all FDA-approved, which were used to treat hypertension to reduce the rate of death, myocardial infarction, and stroke in individuals at high risk for cardiovascular events." (PMID 29403392, 2018). "In contrast to ACE, ACE2 appears to modulate hypertension development through regulation of angiotensin II type 2 receptor (AT2R) and Mas receptor expressions." (PMID 30301188, 2018). "The dose-dependent inhibition of ACE by the DCM fraction, therefore indicates a protective effect against hypertension." (PMID 29449808, 2018). "Angiotensin-converting enzyme (ACE) inhibitors and AT1 blockers are used to prevent hypertension and cardiovascular disease in diabetic patients." (PMID 30425651, 2018). "The renal and cardiac benefits of the ACE inhibitors and AT1 receptor blockers of Ang II in patients with arterial hypertension, cardiovascular illness, and diabetes mellitus seem to be partly independent of their effects in reducing arterial pressure." (PMID 29849615, 2018). "ARBs, like angiotensin converting enzyme (ACE) inhibitors, are marketed for a variety of indications, prominently hypertension." (PMID 30274295, 2018). "AGT and ACE are part of Renin-Angiotensin System pathway (KEGG, map04614), involved in BP homeostasis, fluid-electrolyte balance, and essential hypertension." (PMID 29912962, 2018). "Resveratrol inhibits ACE (angiotensin converting enzyme) and PDE (phosphodiesterase) and upregulates eNOS (endothelial NOS) resulting in a reduction in high blood pressure as per multiple in vivo and in vitro studies." (PMID 30400131, 2018).
Hypertension (continued). "Blocking RAS with angiotensin-converting enzyme (ACE) inhibitors and AT1 blockers represent an established therapy for hypertension, diabetic nephropathy and arteriosclerosis." (PMID 29170528, 2017). "Among AI/AN patients with diabetes and hypertension or chronic kidney disease (CKD), prescription of ACE inhibitors and ARBs was >77% for each year studied." (PMID 28081061, 2017). "Calcium channel blockers are commonly used to treat hypertension, either in combination with other drugs such as inhibitors of AT1R or ACE, or as mono-therapy." (PMID 28514967, 2017). "The use of ACE inhibitors and AT1 receptor blockers is the universally recognized first-line strategy in the treatment of hypertension and cardiovascular disease." (PMID 28174624, 2017). "We commonly use ACE inhibitors or ARBs to block RAS signaling and inhibit cardiac fibrosis in patients with hypertension and cardiac diseases; however, there are few effective therapies that target other pathways involved in the prevention of cardiac fibrosis." (PMID 29259712, 2017). "By using the spontaneously hypertensive rats (SHRs), the possible roles of ACE and Ang II receptors (AT1R, AT2R) in the mediation of the inhibitory effects of EA (8 w) on hypertension and myocardial hypertrophy were also investigated in our present study." (PMID 28293268, 2017). "EPL is a potent antihypertensive drug, a vasodialator and also an angiotensin-converting enzyme (ACE) inhibitor which is widely used for the treatment of hypertension and congestive heart failure." (PMID 28344828, 2017). "Current guidelines on treating hypertension state that initial therapy should include a thiazide-type diuretic, calcium channel blocker (CCB), angiotensin-converting enzyme (ACE) inhibitor, or angiotensin receptor blocker (ARB)." (PMID 28879040, 2017). "Renin (EC 3.4.23.15) converts angiotensinogen to angiotensin I, and it will be converted to biologically active angiotensin II by angiotensin-I converting enzyme (ACE, peptidyldipeptide hydrolase, EC 3.4.15.1), which ultimately leads to hypertension." (PMID 28282929, 2017). "All patients had hypertension and were taking antihypertensive medication, with renin-angiotensin system (RAS) inhibitors including ARBs, ACE inhibitors, and direct renin inhibitors being the most common, followed by calcium channel blockers." (PMID 26839894, 2016). "Both of ACE inhibitors and ARBs, agents blocking RAS, are widely used in the cardiovascular fields for the treatment of heart failure, hypertension and old myocardial infarction." (PMID 27646033, 2016). "Treating diabetes and hypertension is also mandatory to control CKD and, as largely described, the introduction of angiotensin-converting enzyme (ACE) inhibitors and angiotensin receptor blockers (ARBs) is recommended to potentiate nephroprotection." (PMID 27419142, 2016). "Relation between EV-markers and heart failure, corrected for confounders (age, gender, hypertension, diabetes, chronic renal impairment, anemia, MI, Cerebrovascular accident (CVA), beta-blocker, ACE inhibitor, Statins, Aspirin, and diuretics)." (PMID 26820481, 2016). "Hypertension was prevalent in both FFP-treated (95%) and control groups (90%), and ACE inhibitors were frequently used (90% and 85%, resp)." (PMID 26953061, 2016). "Several studies have also revealed that ACE and PAI-1 play a role in CAD occurrence, since both molecules have a critical role in atherosclerosis and hypertension." (PMID 27022914, 2016). "Remarkably, the increase in blood pressure caused by perinatal DDT exposure was normalized by treatment with an ACE inhibitor, captopril, demonstrating that an over-activated RAS is a key mechanism in perinatal DDT exposure–induced hypertension." (PMID 27325568, 2016).